GAS5 (growth arrest specific 5)
Diseases named in the same sentence as GAS5 in open-access papers (continued):
Sharing a sentence is not in itself a finding about the gene and the disease.
Pca (2 papers, 2022 to 2025). "In the PL versus PCa comparison, Humanin maintained high diagnostic performance (AUC = 0.9867), alongside exo-miR-21 (0.9932), plasma-miR-103 (0.9763), and plasma-GAS5 (0.8711), confirming their potential to distinguish early from established malignancy." (PMID 40768089, 2025). "In Pca, mTOR inhibitor-enhanced GAS5 expression in androgen-sensitive cell lines, and GAS5 silencing induced resistance to cytostatic effects of mTOR inhibitors in Pca cells." (PMID 35159022, 2022). "The long non-coding RNA GAS5(Growth Arrest-Specific 5), is known for its tumor-suppressive function, often downregulated in PCa." (PMID 40768089, 2025). "It accurately identified PL as an intermediate state and effectively differentiated BPH from PCa in the terminal nodes based on GAS5 levels." (PMID 40768089, 2025). "Results showed significant downregulation of Humanin and GAS5 in both PL and PCa compared to BPH, supporting their role in early disease transition." (PMID 40768089, 2025). "Conversely, plasma-mir-21 and exo-GAS5 are strongly correlated and primarily aligned along the second principal component, suggesting that these biomarkers may be more informative for distinguish BPH from Pca." (PMID 40768089, 2025). "In addition, GAS5 was significantly increased expressed in exosomes of BPH patients, as also compared to PCa patients." (PMID 40768089, 2025).
prostate diseases (2 papers, 2025). "Combination of circulating Humanin, MOTS-c, GAS5, and exosomal miRNAs provides a promising non-invasive biomarker panel for risk stratification in prostate diseases." (PMID 40768089, 2025).
scrapie (2 papers, 2020 to 2021). A fatal disease of the nervous system in sheep and goats, characterized by pruritus, debility, and locomotor incoordination. "Downregulation of these positive autophagy gene regulators (Becn1, Fbxw7, Gas5 and Atg5) has been described in the CNS of scrapie-infected mice (both wild-type or transgenic) and naturally scrapie infected sheep." (PMID 34283400, 2021).
skin cancer (2 papers, 2017 to 2020). "Taken together, our findings suggest that MM1 has improved antitumor activity in skin cancer cells, and that this is due, at least in part, to the upregulation of lncRNA GAS5 and the enhancement of apoptosis." (PMID 28252643, 2017). "Conversely, overexpression of lncRNA GAS5 inhibited cell proliferation and promoted cell apoptosis in skin cancer cells." (PMID 28252643, 2017). "In contrast, overexpression of lncRNA GAS5 decreases cell viability and promotes the apoptosis of skin cancer cells." (PMID 28252643, 2017). "In this context, it is interesting to note that the expression of lncRNA GAS5 is relatively low in most of the human skin cancer tissues when compared to their adjacent normal tissues." (PMID 28252643, 2017). "In another study, we also confirmed that the same concentration of MM1 could induce increased expression of the tumor suppressor long non-coding RNA, GAS5, compared to magnolol, and exert a greater inhibitory effect on skin cancer cells." (PMID 32850418, 2020). "Therefore, MM1-induced upregulation of lncRNA GAS5 can promote apoptosis and inhibit cell proliferation in skin cancer cells." (PMID 28252643, 2017). "Therefore, lower expression of lncRNA GAS5 appears to prevail in human skin cancer and strategy of targeting lncRNA GAS5 could be considered as another approach for the treatment of skin cancer." (PMID 28252643, 2017). "The expression of lncRNA GAS5 in the skin cancer tissues was found to be lower than that in the adjacent normal tissues in a majority of patients." (PMID 28252643, 2017).
thymoma (2 papers, 2013 to 2015). A neoplasm arising from the epithelial cells of the thymus. "GAS5 (growth arrest-specific transcript 5) was identified using a functional screen through its ability to suppress apoptosis in a mouse thymoma cell line." (PMID 24319682, 2013).
viral infections (2 papers, 2021 to 2025). "While extensive research shows that GAS5 and miRNAs play important roles in viral infections, the literature exploring their interactions and the implications of these interactions in viral pathogenesis remains limited." (PMID 39941145, 2025). "This review explores the dualistic impacts of the GAS5/miRNA network in conditions such as cancer, cardiovascular disease, viral infections, and inflammatory disorders." (PMID 39941145, 2025). "In viral infections, GAS5 generally seems to play a protective role, which is particularly evident in HIV infection, where it can suppress viral replication through the sponging of miR-873 and aid in restoring T cell function via miR-21 modulation." (PMID 39941145, 2025). "In this review, we summarize the role of GAS5/miRNA axes in cancers, cardiovascular diseases, inflammatory diseases, and viral infections." (PMID 39941145, 2025). "These diverse functions position GAS5 as a crucial molecular regulator and a promising target for the development of novel therapeutic strategies against cancer, cardiovascular diseases, inflammatory disorders, and viral infections." (PMID 39941145, 2025). "Finally, while the role of GAS5 in a variety of different viral infections is widely recognized, most of the mechanisms described rely on GAS5/miRNA-mediated axes." (PMID 39941145, 2025). "Modulating GAS5 levels could serve as a novel strategy to mitigate disease progression and improve patient outcomes in viral infections." (PMID 39941145, 2025). "Nevertheless, our findings identify, for the first time, the role of the GAS5-miR-21 axis in CD4 T cell dysregulation in PLHIV and shed light on the molecular aspects of immunomodulation during human viral infections." (PMID 33776993, 2021).
acute lymphoblastic leukemia (1 paper, 2020). Leukemia with an acute onset, characterized by the presence of lymphoblasts in the bone marrow and the peripheral blood. "GAS5 expression was recently found to be tightly linked to therapy progression in acute lymphoblastic leukemia (ALL)." (PMID 33076450, 2020).
acute monocytic leukemia (1 paper, 2024). Acute monoblastic leukemia (AML-M5), is one of the most common subtypes of acute myeloid leukemia (AML) that is either comprised of more than 80% of monoblasts (AML-M5a) or 30-80% monoblasts with (pro)monocytic differentiation (AML-M5b). "GAS5 overexpression enhances cellular energy production and downregulates the pro-inflammatory cytokines IL-1β and IL-6 in human acute monocytic leukemia THP-1 cells." (PMID 38585701, 2024). "Highly expressed lncRNA GAS5 reduces the inflammatory response and the viability of LAMP-1-induced human acute monocytic leukemia THP-1 cells by targeting the miR-222-3p/TIMP3 axis." (PMID 38585701, 2024).
acute respiratory distress syndrome (1 paper, 2022). Progressive and life-threatening pulmonary distress in the absence of an underlying pulmonary condition, usually following major trauma or surgery. "In addition, downregulation of lncRNA GAS5 can decrease ACE2 expression by increasing miR-200c-3p and promote apoptosis of A549 cells, thus promoting the progression of acute respiratory distress syndrome (ARDS)." (PMID 36685535, 2022).
AIDS (1 paper, 2021). A syndrome resulting from the acquired deficiency of cellular immunity caused by the human immunodeficiency virus (HIV). "Furthermore, some ncRNAs have emerged as potential therapeutic targets, some of which include lncRNAs NEAT1, NEAT2 and lnr6RNA, 152742 in tuberculosis; MALAT1, HEAL, SAF, lincRNA-p21, NEAT1, GAS5, NRON, LINC00173 in HIV/AIDS; miRNA-146a in malaria." (PMID 34737736, 2021).
aneurysm (1 paper, 2019). Bulging or ballooning in an area of an artery secondary to arterial wall weakening. "Enhanced glycolytic activity in the aortic wall has been demonstrated to contribute to the pathogenesis of aneurysms 39; nevertheless, whether GAS5 contributes to AAA formation through the regulation of glycolytic activity is unclear." (PMID 31534503, 2019). "Many studies have reported that GAS5 acts as a protein scaffold to regulate the downstream targets of p2119, 20 and phosphatase and tensin homolog (PTEN) 21, 22, which are validated targets associated with SMC proliferation and apoptosis during aneurysm formation." (PMID 31534503, 2019).
aortic stenosis (1 paper, 2019). Aortic valve stenosis is a aortic valve disease caused by the incomplete opening of the aortic valve. "The expression of GAS5 and miR-26a, which interacts with the lncRNA, are up- and down-regulated, respectively, in both plasma samples from patients suffering from aortic stenosis and in aortic ECs treated with ox-LDL." (PMID 31238513, 2019). "GAS5 expression is also increased in atherosclerotic plaques of aortic stenosis patients." (PMID 31238513, 2019).
atrial fibrillation (1 paper, 2025). A disorder characterized by an electrocardiographic finding of a supraventricular arrhythmia characterized by the replacement of consistent P waves by rapid oscillations or fibrillatory waves that vary in size, shape and timing and are accompanied by an irregular ventricular response. "One such example is GAS5, a recently identified lncRNA involved in atrial fibrillation (AF)." (PMID 40900281, 2025).
Atrophy (1 paper, 2019). Any weakening or degeneration, especially through lack of use. "We found that 2310065F04Rik (linc-Myh) resulted down-regulated in both atrophy models while Dancr, Gas5, H19, Igf2os, Airn, MiR22hg, Neat1 and Snhg1 were up-regulated in the late phases of atrophy." (PMID 30649422, 2019).
autism (1 paper, 2021). Persistent deficits in social interaction and communication and interaction as well as a markedly restricted repertoire of activity and interest as well as repetitive patterns of behavior. "Furthermore, we identified ASD subgroup-specific hubs, for example, GAS5|SNORD76 and MTF2 for PDD-NOS or BAZ2A and MTCO2P12|COX2 for autism." (PMID 33719335, 2021).
Autoimmunity (1 paper, 2022). The occurrence of an immune reaction against the organism's own cells or tissues. "Recently, scientists discovered that GAS5 dysregulation has been implicated in the development of autoimmunity states; The most effective medications for treating autoimmune illnesses are glucocorticoids (GC)." (PMID 36310591, 2022).
bacterial sepsis (1 paper, 2020). "GAS5 is abnormally expressed in autoimmune and inflammatory diseases, especially in patients with bacterial sepsis." (PMID 33240872, 2020). "GAS5 is abnormally downregulated in patients with bacterial sepsis." (PMID 33240872, 2020).
benign lung tumors (1 paper, 2015). "In the 19 benign lung tumors, GAS5 expression levels were slightly lower than in the adjacent normal tissues, with an average expression level of 0.936 compared with normal tissues (P = 0.342)." (PMID 25925741, 2015). "Furthermore, our study is the first to elucidate the relationship between GAS5 and benign lung tumors." (PMID 25925741, 2015).
bone marrow fibrosis (1 paper, 2021). "Accordingly, MALAT1 (p = 0.0004) and GAS5 (p = 0.0023) levels positively correlate with a more severe grade of bone marrow fibrosis." (PMID 34638230, 2021). "Among these, high levels of LINC01268, MALAT1 or GAS5 correlate with detrimental clinical variables, such as high count of leukocytes and CD34+ cells, severe grade of bone marrow fibrosis and presence of splenomegaly." (PMID 34638230, 2021). "In particular, high levels of LINC01268, GAS5 and MALAT1, correlated with detrimental features of MF, such as high WBC count, increased number of circulating CD34+ cells, marked LDH activity, presence of splenomegaly and a more severe grade of bone marrow fibrosis." (PMID 34638230, 2021).
breast invasive carcinoma (1 paper, 2025). "On the other hand, GAS5 was significantly downregulated in three types of cancer, which include breast invasive carcinoma (BRCA), kidney chromophobe (KICH), and uterine corpus endometrial carcinoma (UCEC)." (PMID 39958058, 2025).
cardiac arrest (1 paper, 2023). Cessation of breathing and/or cardiac function. "A recent study showed that exosomes isolated from plasma samples of cardiac arrest/cardiopulmonary resuscitation (CA/CPR) patients contained abundant levels of GAS5, which targets inositol polyphosphate-4-phosphatase type II B (INPP4B) through the sponge effect with miR-137." (PMID 38132140, 2023).
cervical adenocarcinoma (1 paper, 2020). An adenocarcinoma arising from the cervical epithelium. "Consistent with the qRT-PCR results, the expression of GAS5 was reduced in most tumour tissues compared to peritumoral tissues in cervical squamous carcinoma tissues and cervical adenocarcinoma tissues." (PMID 32661236, 2020).
chronic obstructive pulmonary disease (1 paper, 2023). A chronic and progressive lung disorder characterized by the loss of elasticity of the bronchial tree and the air sacs, destruction of the air sacs wall, thickening of the bronchial wall, and mucous accumulation in the bronchial tree. "Furthermore, another study on patients with chronic obstructive pulmonary disease by Rubing Mo and collaborators found that LPS induces lncRNA GAS5 expression and release of IL-2, IL-6, IL-10, and TNF-α." (PMID 37047453, 2023).
colitis (1 paper, 2026). Inflammation of the colon. "The levels of tissue GAS5/Gas5 increased in mouse intestinal mucosa after colitis and septic stress, as well as in human intestinal mucosa from patients with IBD." (PMID 41569698, 2026).
colon adenoma (1 paper, 2019). An adenoma that arises from the colon. "It indicated that compared with normal tissues, GAS5 was highly expressed in both colon adenomas and rectal adenomas (P < 0.001 and P < 0.05)." (PMID 30902880, 2019). "TCGA database indicated that compared with normal tissues, GAS5 was highly expressed in both colon adenomas and rectal adenomas." (PMID 30902880, 2019).
dependence (1 paper, 2019). "As for epigenetic profiles, available data has shown that miR-499 was associated with steroid dependence, and a high level of lncRNA growth arrest-specific 5 (GAS5) was claimed to be correlated with poor steroid response." (PMID 31737035, 2019).
endometriosis (1 paper, 2022). The growth of functional endometrial tissue in anatomic sites outside the uterine body. "In this study, we investigated the possible impacts of genetic variations in these ovary-related lncRNAs, PTENP1, GAS5 and UCA1, on endometriosis." (PMID 35901079, 2022). "Since endometriosis shares several features with cancer, we investigated the possible involvement of cancer-related lncRNAs in endometriosis, including UCA1, GAS5 and PTENP1." (PMID 35901079, 2022).
endothelial dysfunction (1 paper, 2025). In vascular diseases, endothelial dysfunction is a systemic pathological state of the endothelium (the inner lining of blood vessels) and can be broadly defined as an imbalance between vasodilating and vasoconstricting substances produced by (or acting on) the endothelium. "The results of this study provide valuable insights into the relationship between Humanin levels and peripheral endothelial dysfunction (ED) in RA patients, while also exploring the role of non-coding RNAs, including GAS5, miR-21, and miR-103." (PMID 39846683, 2025).
fractures (1 paper, 2020). "Of note, OP patients with vertebral fractures (OP_VF; n = 29) showed the most relevant increase in GAS5 expression level compared to both CTR and OP with femoral fractures (OP_FF; n = 14) (p < 0.0001)." (PMID 32967315, 2020).
Hematuria (1 paper, 2021). The presence of blood in the urine. "Only exosomal GAS5 was significantly negatively associated with the tumor stages, tumor grade, and degrees of hematuria (all P < 0.05), whereas, the remaining four exosomal RNAs showed positive correlation with tumor stages, tumor grade, and hematuria degrees (all P < 0.05)." (PMID 33987102, 2021). "Remarkably, we also found the expression of exosomal GAS5 was significantly negatively associated with the tumor grade and degrees of hematuria (all P < 0.05), whereas, the exosomal KLHDC7B, CASP14, PRSS1, and MIR205HG showed positive correlation with tumor grade and hematuria degrees." (PMID 33987102, 2021).
hepatitis C virus infection (1 paper, 2021). A viral infection caused by the hepatitis C virus. "GAS5 is a single-stranded lncRNA, and one study demonstrated that the mRNA expression of GAS5 was elevated in response to hepatitis C virus infection and that GAS5 impaired virus replication by the interaction between truncated-GAS5 and HCV NS3 protein in human cells." (PMID 34045524, 2021).
hepatoblastoma (1 paper, 2024). Hepatoblastoma (HB) is a malignant hepatic tumor and is the most common pediatric liver cancer. "Conversely, Gas5 was downregulated in HB cells, inducing cell apoptosis and inhibiting tumor growth through the activation of the CHOP-dependent endoplasmic reticulum stress pathway in human hepatoblastoma HepG2 cells." (PMID 38390281, 2024).
hippocampal atrophy (1 paper, 2023). "Interestingly, the expression of GAS5 was negatively correlated with hippocampal volume, suggesting that GAS5 may play an important regulatory role in hippocampal atrophy." (PMID 36947499, 2023).
Hyperammonemia (1 paper, 2022). An increased concentration of ammonia in the blood. "Our data revealed the roles of lncRNAs, ZFAS1, and GAS5, on neuronal cell death and neural structure in hyperammonemia in in vivo and in vitro conditions." (PMID 35464767, 2022). "Taken together, our results suggest that both ZFAS1 and GAS5 exert proapoptotic effects during NH4Cl-induced hyperammonemia." (PMID 35464767, 2022). "Thus, ZFAS1 and GAS5 lncRNAs may contribute to hyperammonemia-induced neuronal injury and cell death." (PMID 35464767, 2022).
idiopathic pulmonary fibrosis (1 paper, 2024). Idiopathic pulmonary fibrosis (IPF) is a nonneoplastic pulmonary disease that is characterized by the formation of scar tissue within the lungs in the absence of any known cause. "A notable example is GAS5, which functions as a competing endogenous RNA (ceRNA) in idiopathic pulmonary fibrosis (IPF)." (PMID 39201688, 2024).
injury (1 paper, 2019). Damage inflicted on the body as the direct or indirect result of an external force, with or without disruption of structural continuity. "The LncRNA GAS5 (growth arrest-specific 5) is currently under intense investigation because of its dysregulation in various diseases, including several types of cancer, childhood pneumonia, and traumatic brain injury." (PMID 31248165, 2019).
kidney cancer (1 paper, 2022). Primary or metastatic malignant neoplasm involving the kidney. "For example, KCQN1OT1 and MALAT-1 are the kidney cancer-associated onco-lncRNAs, and H19 and GAS5 are the kidney cancer-associated tumor suppressive lncRNAs." (PMID 34983363, 2022).
laryngeal neoplasm (1 paper, 2021). A benign or malignant neoplasm involving the larynx. "Notably, the model predicts that lncRNA GAS5, which scored second, inhibits proliferation and metastasis of laryngeal neoplasms by regulating the PI3K/AKT/mTOR signaling pathway, according to a recent study in 2020." (PMID 35058974, 2021).
malignant mesothelioma (1 paper, 2020). A malignant neoplasm of the pleura or peritoneum, arising from mesothelial cells. "GAS5 is verified as an appropriate circulating marker for the supplement of calretinin and mesothelin to detect malignant mesothelioma." (PMID 32435497, 2020). "The benefit of GAS5 for the detection of malignant mesothelioma at early stages needs to be validated in a prospective study." (PMID 32435497, 2020). "GAS5 was identified in silico and verified in cell lines as well as human liquid biopsies as an appropriate circulating marker for the supplement of calretinin and mesothelin to detect malignant mesothelioma." (PMID 32435497, 2020).